H2AX (H2A.X variant histone)
Description:
Variant histone H2A which replaces conventional H2A in a subset of nucleosomes. Nucleosomes wrap and compact DNA into chromatin, limiting DNA accessibility to the cellular machineries which require DNA as a template. Histones thereby play a central role in transcription regulation, DNA repair, DNA replication and chromosomal stability. DNA accessibility is regulated via a complex set of post-translational modifications of histones, also called histone code, and nucleosome remodeling. Required for checkpoint-mediated arrest of cell cycle progression in response to low doses of ionizing radiation and for efficient repair of DNA double strand breaks (DSBs) specifically when modified by C-terminal phosphorylation.
Synonyms: H2a/x; H2AFX; H2A.X
Tractability: PROTAC: UniProt records ubiquitination sites on it; ubiquitination databases record sites on it.
Gene: Protein-coding gene on chromosome 11 (119,093,874 to 119,095,465, reverse strand). Ensembl gene ENSG00000188486.
Subcellular location: Nucleus; Chromosome
Subcellular location (Human Protein Atlas): Nucleoplasm; Nuclear speckles
Pathways (Reactome):
Gene expression (Transcription): B-WICH complex positively regulates rRNA expression; DNA methylation; ERCC6 (CSB) and EHMT2 (G9a) positively regulate rRNA expression; MLL4 and MLL3 complexes regulate expression of PPARG target genes in adipogenesis and hepatic steatosis; NoRC negatively regulates rRNA expression; PRC2 methylates histones and DNA; RNA Polymerase I Promoter Escape; RNA Polymerase I Promoter Opening; RUNX1 regulates genes involved in megakaryocyte differentiation and platelet function; RUNX1 regulates transcription of genes involved in differentiation of HSCs; Regulation of endogenous retroelements by KRAB-ZFP proteins; Regulation of endogenous retroelements by Piwi-interacting RNAs (piRNAs); Regulation of endogenous retroelements by the Human Silencing Hub (HUSH) complex; SIRT1 negatively regulates rRNA expression; Transcriptional regulation by small RNAs
DNA Repair: Cleavage of the damaged purine; Cleavage of the damaged pyrimidine; Nonhomologous End-Joining (NHEJ); Processing of DNA double-strand break ends; Recognition and association of DNA glycosylase with site containing an affected purine; Recognition and association of DNA glycosylase with site containing an affected pyrimidine; Recruitment and ATM-mediated phosphorylation of repair and signaling proteins at DNA double strand breaks
Chromatin organization: CHD1 and CHD2 subfamily; CHD6, CHD7, CHD8, CHD9 subfamily; ChAHP complex assembly; Interaction of NuRD complexes with transcription factors; NuRD complex assembly; RMTs methylate histone arginines
Cell Cycle: Condensation of Prophase Chromosomes; Deposition of new CENPA-containing nucleosomes at the centromere; G2/M DNA damage checkpoint; Inhibition of DNA recombination at telomere; Packaging Of Telomere Ends
Developmental Biology: Activation of anterior HOX genes in hindbrain development during early embryogenesis; Chromatin modifications during the maternal to zygotic transition (MZT); Replacement of protamines by nucleosomes in the male pronucleus; Transcriptional regulation of granulopoiesis
Signal Transduction: Activated PKN1 stimulates transcription of AR (androgen receptor) regulated genes KLK2 and KLK3; Estrogen-dependent gene expression; Formation of the beta-catenin:TCF transactivating complex
and 12 more pathways
Gene Ontology:
Molecular function: chromatin-protein adaptor activity; enzyme binding; histone binding; protein binding; DNA binding; structural constituent of chromatin; damaged DNA binding; protein heterodimerization activity
Biological process: DNA damage checkpoint signaling; DNA damage response; protein localization to site of double-strand break; double-strand break repair; heterochromatin formation; nucleosome assembly; positive regulation of DNA repair; response to ionizing radiation
Cellular component: centrosome; chromosome; chromosome, telomeric region; extracellular exosome; nuclear speck; nucleoplasm; nucleus; site of DNA damage; site of double-strand break; nucleosome; chromatin; condensed nuclear chromosome; male germ cell nucleus; replication fork; XY body
Genetic constraint (gnomAD): Loss-of-function variants: 2 observed, 8.04 expected, observed/expected ratio (o/e) 0.25, 90% interval 0.1 to 0.78. That is too few expected variants to judge how well the gene tolerates losing a copy. Missense variants: 105 observed, 208.53 expected, observed/expected ratio (o/e) 0.5, 90% interval 0.43 to 0.59. Synonymous variants: 110 observed, 104.04 expected, observed/expected ratio (o/e) 1.06, 90% interval 0.9 to 1.24.
Homologues: Orthologues: chimpanzee H2AX (100% identical), macaque H2AX (100% identical), rabbit H2AX (100% identical), dog H2AX (99% identical), pig H2AX (99% identical), mouse H2ax (97% identical), rat H2ax (97% identical), zebrafish h2ax1 (84% identical), Caenorhabditis elegans his-47 (78% identical), Caenorhabditis elegans his-12 (76% identical), Caenorhabditis elegans his-16 (76% identical), Caenorhabditis elegans his-3 (76% identical), and 7 more. Paralogues in human: H2AC21 (83% identical), H2AC6 (83% identical), H2AC11 (83% identical), H2AC13 (83% identical), H2AC15 (83% identical), H2AC16 (83% identical), H2AC17 (83% identical), H2AC18 (83% identical), H2AC19 (83% identical), H2AC20 (83% identical), H2AC25 (83% identical), H2AJ (83% identical), and 15 more.
Diseases named in the same sentence as H2AX in open-access papers:
H2AX is named in the same sentence as 254 diseases in open-access papers, as found by Europe PMC text mining. Sharing a sentence is not in itself a finding about the gene and the disease. The quoted sentences say what the papers report.
breast carcinoma (116 papers, 2006 to 2026). "RNF8 was demonstrated to activate Ubc13 and recruit K63-linked poly-ubiquitin conjugation to histones H2A/H2AX, thus contributing to breast cancer predisposition." (PMID 35874839, 2022). "Spearman correlation analysis of breast cancer subgroups revealed that the association between nuclear Cyclin E and γ-H2AX expression was strongest in ER/PR−HER2+ (r = 0.86, P < 0.001) and TNBC (r = 0.71, P < 0.001)." (PMID 32964114, 2020). "While there are no data for myeloma linking γH2AX foci formation with telomere shortening, in breast cancer patients, γ-H2AX foci were linked to shorter telomeres, which were in turn associated with poorer prognosis of triple-negative breast cancer patients." (PMID 31311193, 2019). "The data shows that resveratrol treatment results in reduction of S-phase cell cycle and induction of γ-H2AX, which is a hallmark of DNA damage after UV irradiation in breast cancer cells, MDA-MB-231." (PMID 28377996, 2017). "We found that while γ-H2AX levels increased after single treatment, the combination treatment caused a further increase in both breast cancer lines." (PMID 22457814, 2012). "The p.Arg215Trp variant, suggested to impair NBN binding to histone γ-H2AX, was observed in one breast cancer case and one healthy control." (PMID 19523210, 2009). "Here we report that L1 has genome-destabilizing effects indicated by an accumulation of γ-H2AX foci, an early response to DNA strand breaks, in association with induction of apoptosis in breast cancer cells." (PMID 16670018, 2006). "For example, it has been demonstrated that bee venom induces the interaction between phosphorylated histone variant H2AX and the intracellular site of β-actin in liver and breast cancer cells, indicating its involvement in modulating intracellular signaling pathways related to apoptosis." (PMID 39203027, 2024). "Moreover, previous studies have indicated that the G allele of H2AX‐rs7759 is related to an increased risk of breast cancer." (PMID 35235704, 2022). "Together, the results from nuclear morphology (nuclear fragmentation and/or condensation), phospho-H2AX detection (an earlier indicator of apoptosis), and PI uptake (a late apoptosis indicator) clearly demonstrated the apoptosis in breast cancer cells caused by BI 2536." (PMID 22309939, 2012). "We report that L1 has genome-destabilizing effects indicated by an accumulation of γ-H2AX foci, an early response to DNA strand breaks, in association with an abnormal cell cycle progression through a G2/M accumulation and an induction of apoptosis in breast cancer cells." (PMID 16670018, 2006). "In AZD4573-sensitive breast cancer cells, the numbers of γ-H2AX foci in EdU-positive cells were increased by 3.5–4.8 fold within 3 h following AZD4573 treatment compared to controls." (PMID 40713627, 2025). "This allows ATM to phosphorylate S139 of H2AX (γH2AX) and promote H2AX-binding with a mediator of DNA damage checkpoint 1 (MDC1) via the breast cancer-associated C-terminal domain as shown via X-ray diffraction." (PMID 38338953, 2024). "Since γ-H2AX was described to be accumulated in patients with a basal-like subtype of breast cancer, we compared the distribution of the basal-like subtype in tumors with low and high γ-H2AX expression levels." (PMID 38502354, 2024). "A study by Gruosso and coauthors revealed a novel mechanism of the relation between the content of H2AX, free radicals (ROS), and Nrf2 in the cells of breast cancer (BC)." (PMID 36980990, 2023). "Our findings reveal a role for histone H2AX in controlling the metastatic ability of breast cancer cells via maintenance of HK2-driven glycolysis." (PMID 35260660, 2022).
breast carcinoma (continued). "Our study reveals unprecedented evidence of a role for histone H2AX in promoting metastatic ability of invasive breast cancer cells, potentially via transcriptional regulation of hexokinase-2 and glycolysis maintenance." (PMID 35260660, 2022). "Utilizing models of experimental metastasis, we found that H2AX silencing halts progression of metastatic breast cancer cells MDA-MB-231." (PMID 35260660, 2022). "We further investigated the expression level of phosphorylated histone H2AX (γH2AX) in breast cancer cells." (PMID 34217266, 2021). "Mei and colleagues found that miR-15a, 15b, and 16 influence radiosensitivity of MCF7 and MDA-MB-231 breast cancer cells, observable through the enhanced duration of H2AX foci and release of the G2 arrest induced by radiation." (PMID 34804940, 2021). "Recently, it has been shown that ATM knockdown sensitized breast cancer cells to irradiation, and reduced phosphorylation of γ-H2AX, highlighting a strong relationship between ATM, DNA repair pathway and radioresistance." (PMID 34268251, 2021). "Mechanistically, we showed that BOLD-100 induces G2/M cells cycle arrest, ROS and gamma-H2AX in both ER+ and ER− breast cancer cells." (PMID 32947941, 2020). "In our present work, we established a relatively radio-resistant breast cancer cell line and found that γ-H2AX kinetic was significantly altered in the cells, indicating an elevated DNA damage repair response." (PMID 32174787, 2020). "Consistently, our data show an increase in DNA damage in breast cancer cells, as shown by an increase in gamma-H2AX." (PMID 32947941, 2020). "Increased chromosomal radiosensitivity, quantified by γ-H2AX/53BP and γ-H2AX immunofluorescence microscopy were observed in breast cancer patients with an adverse acute skin reaction compared to those with normal skin reaction after radiotherapy." (PMID 33013205, 2020). "Caspase-3 and γ-H2AX staining showed SMIP004 promoted breast cancer cells apoptosis and increased DNA damage in vivo after radiation." (PMID 30760284, 2019). "We also immunohistochemically detected p16 and γ-H2AX in skin tissue samples from healthy volunteers and patients with breast cancer receiving radiation therapy." (PMID 32117790, 2019). "Since doxorubicin (DOX) is known to cause DNA damage, we first examined the effects of doxorubicin on phosphorylation of H2AX (Ser139), a key DNA damage signal, in human breast cancer cells, MDA-MB-231 and MCF-7." (PMID 30744690, 2019). "Treatment of human breast cancer cells with DOX increased the level of phosphor-H2AX (Ser139) in a dose- and time-dependent manner." (PMID 30744690, 2019). "Taken together, these results demonstrate that OTS193320 plays a crucial role in the regulation of γ-H2AX production in human breast cancer cells." (PMID 30159125, 2018). "The immunofluorescence results showed that p-H2AX intensity was significantly elevated following paclitaxel or ADQ treatment in both breast cancer cell lines." (PMID 30333750, 2018). "Consistent with the cell cycle findings, ADQ synergistically interacted with paclitaxel to enhance p-H2AX expression in both breast cancer cell lines." (PMID 30333750, 2018). "Immunofluorescent quantification of the phosphorylation of histone H2AX was used as an indicator of DNA damage in breast cancer cells treated with stress hormones." (PMID 28340615, 2017). "Etoposide treatment (a positive control for DNA damage induction) resulted in an elevation in DNA breaks and activation of DNA damage response (DDR) with increased phosphorylation of both ATM and H2AX in three breast cancer cells examined." (PMID 28213701, 2017).
breast carcinoma (continued). "The NCI-60 cell lines also show a wide variety of basal % γ-H2AX values (right hand panel), from a low of 0.2% found in NHFs and the breast cancer cell line MCF7 to greater than 4% observed in the acute myeloid leukemia cell line HL-60(TB)." (PMID 28158293, 2017). "All breast cancer cell lines treated with either riluzole or BAY 36-7620 had an increased percentage of cells positive for γ-H2AX foci as detected by immunofluorescence." (PMID 28591718, 2017). "Escherichia coli (a member of the Enterobacteriaceae family) and Staphylococcus epidermidis, isolated from breast cancer patients, were shown to induce DNA double-stranded breaks in HeLa cells using the histone-2AX (H2AX) phosphorylation (γ-H2AX) assay." (PMID 27342554, 2016). "SIRT1 knockdown reproduced the effects of combinatorial resveratrol and pterostilbene-induced SIRT1 down-regulation through inhibition of both telomerase activity and γ-H2AX expression in HCC1806 breast cancer cells." (PMID 26459286, 2015). "In the sensitive luminal breast cancer cell line SKBr3, the endogenous levels of H2AX phosphorylated on Ser139 was much higher compared to all other cell lines." (PMID 25104095, 2014). "Previously we demonstrated that expression of NeuT in immortalized breast cancer epithelial cells MCF10A leads to significant downregulation of the major DNA repair factor histone H2AX." (PMID 25252808, 2014). "In that study, the authors have observed a subset of patients with triple negative breast cancer based on γ-H2AX positivity in the formalin fixed tumor samples and embedded breast cancer cell lines." (PMID 23617930, 2013). "We also detected the the localization of 53BP1 and H2AX foci in breast cancer before and after the treatment of 5-Fu." (PMID 24040364, 2013). "We have previously reported that sporadic breast cancer tissues exhibit significant alteration in H2AX gene copy number." (PMID 21463514, 2011). "Suppression of miR-18a after the transfection of miR-18a inhibitor not only increased the expression of ATM in both breast cancer cell lines, but also dramatically increased the levels of phosphorylation levels of H2AX (γ-H2AX) and 53BP1 (p-53BP1)." (PMID 21980462, 2011). "In breast cancer, positive γ-H2AX expression was correlated with the basal-like phenotype." (PMID 38502354, 2024). "Besides, H2AX promotes metastatic progression in breast cancer cells by preserving glycolysis via hexokinase-2." (PMID 38566813, 2024). "Hence, phosphorylated histone H2AX (γ-H2AX) levels after Doxorubicin or Olaparib treatment of breast cancer cells were examined." (PMID 37298108, 2023). "Specifically, Escherichia coli (a member of the Enterobacteriaceae family) and Staphylococcus epidermidis, isolated from breast cancer patients, were shown to induce DNA double‐stranded breaks in HeLa cells using the histone‐2AX (H2AX) phosphorylation (γ‐H2AX) assay." (PMID 37539732, 2023). "Furthermore, inhibiting mTORC1/2 using PP242 induced the formation of γ-H2AX foci in inflammatory breast cancer cells." (PMID 35860572, 2022). "In addition, this combined treatment has also decreased the γ-H2AX and telomerase expression leading to significant growth inhibition, apoptosis, and cell cycle arrest in the treated breast cancer cells." (PMID 35327559, 2022). "Our results showed that CB treatment increased the p53BP1 and γ-H2AX foci in breast cancer cells." (PMID 35610507, 2022). "Healthy BRCA1 mutation carriers and non-carriers showed a similar level of γ-H2AX nuclear foci after exposure to radiation, indicating γ-H2AX nuclear foci assay is not likely able to distinguish women at a high risk of hereditary breast cancer." (PMID 33013205, 2020).